ECM1 (extracellular matrix protein 1)
Diseases named in the same sentence as ECM1 in open-access papers (continued):
Sharing a sentence is not in itself a finding about the gene and the disease.
ovarian carcinoma (12 papers, 2010 to 2025). A malignant neoplasm originating from the surface ovarian epithelium. "Integrin X2 and the AKT/FAK/Rho/cytoskeleton signaling pathways are implicated in the promotion of ovarian cancer by the bioactive recombinant ECM1 (ECM1a) subtype." (PMID 37124542, 2023). "In ovarian cancer, ECM1 was associated with cisplatin resistance, and high levels of ECM1 in the stroma can induce normal fibroblasts transformation and then promote tumor progression." (PMID 36408224, 2022). "Because one of the biggest obstacles in the treatment of most cancers, including ovarian cancer, is platinum resistance, we first examined the cisplatin sensitivity of the ECM1-associated cell lines established in this study." (PMID 34244494, 2021). "Mechanistically, we found that VII can bind to RORα, enhance its protein stability, and inhibit the FAK/AKT/GSK3β signaling pathway in ovarian cancer cells resistant to PARP inhibitors through the RORα/ECM1/VEGFR2 signaling axis." (PMID 38725854, 2024). "The results also showed that the expression inhibition of VEGFR2 partially reversed the impact of ECM1 overexpression on PS VII's intervention on ovarian cancer cell proliferation, angiogenesis, glycolysis, and other functions." (PMID 38725854, 2024). "Based on this, we confirmed once again in clinical samples that the RORα/ECM1/VEGFR2 signaling axis is closely associated with PARP inhibitor resistance, disease progression, and survival prognosis in ovarian cancer." (PMID 38725854, 2024). "Further analysis of clinical data revealed that low expression of RORα and high expression of ECM1 and VEGFR2 were all associated with poor overall survival (OS) and progression-free survival (PFS) in patients with PARP inhibitor-resistant ovarian cancer." (PMID 38725854, 2024). "Extracellular matrix protein-1 (ECM1) secreted by ovarian cancer cells promotes CAF activation by increasing the expression of FAP and α-SMA." (PMID 39802952, 2024). "The same study that showed ECM1 secretion by ovarian cancer promotes CAF development and chemoresistance also tested the effects of the algae-extracted compound Wentilactone A." (PMID 39802952, 2024). "Herein, we show that a secondary metabolite WA from Sargassum reverses the cisplatin resistance of ovarian cancer cells through inhibition of the NF-κB-activated signaling pathway to induce the expression of ECM1." (PMID 36145166, 2022). "Wentilactone A reverses the NFκB/ECM1 signaling-induced cisplatin resistance through the inhibition of IKK/IκB in ovarian cancer cells, which provides the possibility of cooperation with cisplatin to improve the cancer patient survival." (PMID 36145166, 2022). "To investigate how ECM1 is regulated in cancer cells, we first examined ECM1 protein expression by quantitative reverse transcription (RT)-PCR (qRT-PCR) in seven human ovarian cancer cell lines and one normal human ovarian surface epithelial (HOSE) cell line." (PMID 34244494, 2021). "The increase in expression of ECM1 was validated by Western blot in all of the ovarian cancer serum pools." (PMID 20546617, 2010). "Therefore, we believe that the RORα/ECM1 axis plays an important role in PS VII's treatment of PARP inhibitor-resistant ovarian cancer." (PMID 38725854, 2024). "Overall, Wentilactone A reduces ECM1 secretion to reverse cisplatin sensitivity in ovarian cancer." (PMID 39802952, 2024). "In addition, downregulation of ECM1 in ovarian cancer cells also restored the impact of PS VII on ECAR and OCR." (PMID 38725854, 2024). "Moreover, we have discovered the specific mechanism by which PS VII reverses PARP inhibitor resistance in ovarian cancer through the RORα/ECM1/VEGFR2 signaling axis." (PMID 38725854, 2024). "Its potential function may hinder glycolysis and angiogenesis in PARPi resistant ovarian cancer cells, which is associated with PS VII binding and stabilizing RORα expression, further inhibiting ECM1 and blocking the VEGFR2/FAK/AKT/GSK3β signaling pathway." (PMID 38725854, 2024).
ovarian carcinoma (continued). "Interestingly, ECM1 was identified in two proteomic analyses of ovarian cancer ascites cells, and was also highly enriched in the conditioned media from ovarian cancer cell lines and in chemoresistant ovarian tumor tissue." (PMID 20546617, 2010). "ECM1 was identified in two iTRAQ® experiments, with an ovarian cancer-to-control ratio of ~1.6." (PMID 20546617, 2010). "Additionally, we found that PS VII potentially hindered glycolysis and angiogenesis in PARPi-resistant ovarian cancer cells by binding and stabilizing the expression of RORα, thus further inhibiting ECM1 and interfering with the VEGFR2/FAK/AKT/GSK3β signaling pathway." (PMID 38725854, 2024). "Therefore, our research further reveals that ECM1 may play a role as a member of a complex regulatory network in cancer cells and plays an important role in reversing ovarian cancer PARP inhibitor resistance through PS VII." (PMID 38725854, 2024). "A total of 232 high-grade serous ovarian cancer patient tissue chips (including 114 PARP inhibitor-resistant patients and 118 PARP inhibitor-sensitive patients) were selected to evaluate the clinical significance of RORα, ECM1, and VEGFR2 in ovarian cancer." (PMID 38725854, 2024). "PS VII, a targeted drug for the RORα/ECM1/VEGFR2 signaling axis, is expected to become a new generation of ovarian cancer therapeutic agents." (PMID 38725854, 2024). "The results showed that ECM1 can rescue the expression levels of p-FAK, p-AKT, and p-GSK3β in PARP inhibitor-resistant ovarian cancer cells." (PMID 38725854, 2024). "More recently, ECM1 secretory isoform binds to integrin αxβ2, which activates the AKT/FAK/Rho pathway in ovarian cancers." (PMID 35784388, 2022). "The proteins ECM1, LBP1, and PRG4 all warrant further investigation into their specificity as potential biomarkers for ovarian cancer, using an ELISA or other methods suitable for use in whole (undepleted) serum." (PMID 20546617, 2010). "The inhibition of ECM1 expression was also observed to rescue cell migration and angiogenesis and to restore the glucose uptake and lactate, ATP, and NADPH efficacy of PS VII against PARP inhibitor-resistant ovarian cancer cells under RORα downregulation." (PMID 38725854, 2024). "In addition, the expression of ECM1 and VEGFR2 in tissue chips was also closely related to PARP inhibitor resistance in ovarian cancer." (PMID 38725854, 2024). "In addition, five new proteins with increased expression in ovarian cancer sera were identified: alpha-1-antitrypsin (AAT), apolipoprotein E (APOE), extracellular matrix protein-1 (ECM1), inter-alpha globulin inhibitor-H3, orosomucoid-2 (ORM2)." (PMID 20546617, 2010). "Therefore, we conclude that PS VII may hinder the binding of ECM1 to VEGFR2 and inhibit the FAK/AKT/GSK3β signaling pathway in PARP inhibitor-resistant ovarian cancer cells by activating RORα, affecting functions such as glycolysis and angiogenesis, and ultimately improving its resistance treatment." (PMID 38725854, 2024).
thyroid cancer (10 papers, 2013 to 2025). "In addition, some studies suggest ECM1 expression may be incorporated into a scoring model to predict high-risk thyroid cancers." (PMID 24023917, 2013). "Though a previous study showed that the level of ECM1 mRNA expression was higher in TNM stage I thyroid cancers than in stage II and III tumors." (PMID 24779890, 2014). "Regarding the ECM1 gene, it was reported not only in thyroid cancer but also in other solid tumors." (PMID 32610693, 2020). "Therefore, the association between VDR to ECM1 and TMPRSS4, suggested a potential role of VDR in thyroid carcinoma." (PMID 28092021, 2017). "ECM1 over-expression has been reported in several malignancies, including invasive ductal breast carcinomas, esophageal squamous cell carcinomas, gastric cancers, colorectal, lung and thyroid cancers." (PMID 24023917, 2013). "Additional in vitro studies demonstrated that 25(OH)D3 was able to decrease proliferative activity of follicular thyroid cells and modulate expression of ECM protein-1 (ECM1) and the type II transmembrane serine protease-4 (TMPRSS4), two independent predictor of thyroid carcinoma." (PMID 28092021, 2017).
bladder cancer (8 papers, 2022 to 2025). "However, the Eubacterium ruminantium group (genus) also upregulates extracellular matrix protein 1 in bladder tissues, increasing bladder cancer risk by raising matrix metalloproteinase 9 expression through the ERK1/2 phosphorylation pathway." (PMID 39076985, 2024). "CAG:581 has contributed to the development of bladder cancer through activating the extracellular matrix protein 1-matrix metalloproteinase 9 pathway." (PMID 36765767, 2023). "Another cohort study reported that upregulated urinary Eubacterium abundance alters extracellular matrix protein 1 (ECM1) in bladder tissue, enhancing matrix metalloproteinase 9 (MMP9) expression via the ERK1/2 phosphorylation pathway, ultimately facilitating bladder cancer progression." (PMID 40708946, 2025).
hepatocellular carcinoma (8 papers, 2014 to 2024). A malignant tumor that arises from hepatocytes. "Elevated ECM1 expression has been observed in several cancers, such as thyroid, gastric, colorectal, and lung carcinoma, invasive ductal breast carcinomas, hepatocellular cancer, and more." (PMID 39078811, 2024). "Our results are consistent with the ECM1 expression status observed in hepatocellular cancer and suggest that ECM1 expression correlates to carcinogenesis and invasiveness of tumor cells." (PMID 24779890, 2014). "However, in hepatocellular cancer, ECM1 gene silencing increases anchorage-independent growth." (PMID 29858602, 2018).
Azoospermia (7 papers, 2017 to 2024). Absence of any measurable level of sperm,whereby spermatozoa cannot be observed even after centrifugation of the semen pellet. "A study involving 119 seminal plasma samples from men with both normal spermatogenesis and azoospermia identified ECM1, along with TEX101, as key in differentiating between OA and NOA." (PMID 38689732, 2024). "As a result, the combination of TEX101 and ECM1 showed an almost exclusive discrimination between the azoospermia conditions." (PMID 37568830, 2023). "Concentration of ECM1 below 2.3 μg/mL of seminal plasma indicates obstructive azoospermia with a specificity of 73% and a sensitivity of 100%." (PMID 37568830, 2023). "This suggests that ECM1 plays a critical role in the molecular processes underlying NOA and has potential clinical significance in diagnosing and differentiating various forms of azoospermia." (PMID 38689732, 2024). "All azoospermia cases diagnosed as NOA by ECM1 ≥ 2.3 μg/mL and TEX101 ≥ 0.9 ng/mL will thus be correct (32 patients), while 19% of patients diagnosed as OA based on ECM1 < 2.3 μg/mL and TEX101 < 0.9 ng/mL (eight patients in the current set) will be actually NOA (false negatives)." (PMID 28330469, 2017). "The combination of a concentration of TEX101 > 0.9 ng/mL and epididymis-specific protein ECM1 > 2.3 μg/mL provided 81% sensitivity at 100% specificity for differentiating between non-obstructive and obstructive azoospermia, thus eliminating the majority of diagnostic testicular biopsies." (PMID 28330469, 2017). "For detection of the type of azoospermia, proteins can be used individually (L-PGDS, NPC2 or ECM1) or, more effectively, in a combination of two or more detected proteins with different expressions in the male genital tract." (PMID 37568830, 2023). "The same group developed a multiplex selected reaction monitoring (SRM) assay to detect the level of testis-expressed protein 101 (TEX101) and epididymis-expressed extracellular matrix protein 1 (ECM1) to distinguish men with obstructive azoospermia from those with non-obstructive azoospermia." (PMID 29704899, 2018).
colorectal cancer (7 papers, 2018 to 2024). A primary or metastatic malignant neoplasm that affects the colon or rectum. "ECM1 was oncogenic, which promoted colorectal cancer proliferation and progression via PI3K/AKT/GSK3B/Snail pathway signal." (PMID 38062443, 2023). "In prior reports, extracellular matrix protein 1 (ECM1) upregulation has been reported in colorectal cancer (CRC) patient tumor tissues, and has been suggested to be related to the metastatic progression of CRC, although the underlying mechanisms have yet to be clarified." (PMID 35574325, 2022).
breast tumors (6 papers, 2005 to 2024). "In breast tumors, high ECM1 expression is associated with poor prognosis, and ECM1 confers endocrine resistance on ER+ tumors that may be mediated by SRC." (PMID 36768435, 2023). "In both datasets, approximately 10–20% of luminal types of breast tumors harbored ECM1 amplification." (PMID 35784388, 2022). "Of the ECM1, -2, -3, and -4 breast tumor subgroups defined in our previous analysis, we focused on ECM3 because it was clearly detectable in every dataset analyzed." (PMID 23441215, 2013). "It is plausible to speculate that both macrophages and adipocytes play significant roles in delivering sEVs containing elevated levels of ECM1 to the breast tumors, although the relative contributions of these sEVs cannot be clearly defined." (PMID 38402239, 2024). "ECM1 is overexpressed in many epithelial tumours including 73% of breast tumours analyzed." (PMID 15642117, 2005). "Finally, an interrogation of the GSE59515 dataset from a study with comparative gene expression profiling of ER+ breast tumors receiving neoadjuvant letrozole treatment for 2 weeks showed that the expression of ECM1 is increased in post-treatment tumors compared to pre-treatment tumors." (PMID 35784388, 2022).
lung carcinoma (6 papers, 2019 to 2025). "Exosomal proteomes have identified several exosomal proteins, including CD317, EGFR, leucine-rich a2-glycoprotein (LRG1), alpha-2-HS-glycoprotein (AHSG), and extracellular matrix protein 1 (ECM1), that hold the potential to serve as indicators for lung cancer early detection." (PMID 40559625, 2025).
prostate carcinoma (6 papers, 2015 to 2025). A carcinoma that arises from epithelial cells of the prostate gland. "Mechanistically, ECM1 interacts with the enolase 1 (ENO1) receptor on the prostate cancer cell membrane, leading to its phosphorylation at the Y189 site." (PMID 39563492, 2025). "Taken together, a potential mechanism is identified through which osteoblast‐derived ECM1 drives resistance in bone metastatic prostate cancer under ENZ treatment." (PMID 39563492, 2025). "Mechanistically, ECM1 interacts with the ENO1 receptor on the prostate cancer cell membrane, leading to its phosphorylation, contributing to the activation of the MAPK signaling pathway, resulting in the development of tumor resistance." (PMID 39563492, 2025). "Other studies also found that ECM1 was down-regulated in some tumors, such as esophageal cancer and prostate cancer, as a tumor suppressor." (PMID 38546916, 2024). "DKK3 silencing reduced the level of extracellular matrix protein-1 (ECM-1) in prostate stromal cell-conditioned media but increased it in epithelial cell-conditioned media, and recombinant ECM-1 inhibited TGFBI-induced prostate cancer cell invasion." (PMID 29858602, 2018). "We found that ECM-1 was more highly expressed in prostate cancer than in benign prostate epithelium." (PMID 29858602, 2018). "Several promising biomarkers for male infertility and prostate cancer include ECM1, TEX101, LDHC, TKTL and ACPP proteins, and prostate specific antigen (PSA), TMPRSS2-ETS." (PMID 26097523, 2015). "Here, it is demonstrated that under ENZ treatment, osteoblasts in the bone microenvironment secrete increased levels of extracellular matrix protein 1 (ECM1), which affects surrounding prostate cancer cells, promoting tumor cell proliferation and anti‐androgen resistance." (PMID 39563492, 2025). "In addition, prostate cancer cells extracted from bmCRPC tumor tissue showed activation of the MAPK pathway after treatment with ECM1." (PMID 39563492, 2025). "However, there was a positive correlation of Dkk-3 and ECM-1 in cancer stroma, and ECM1 gene expression correlated with increased relapse-free survival of prostate cancer patients, suggesting ECM-1 has a tumor-inhibitory function." (PMID 29858602, 2018). "Moreover, DKK3 depletion in WPMY-1 prostate stromal cells is reported to increase TGF-β signaling activity and extracellular matrix protein 1 (ECM-1) secretion, and stromal cell-conditioned media from DKK3-deficient WPMY-1 cells was found to inhibit prostate cancer cell invasion." (PMID 36671452, 2022). "The improvement in RWPE-1 acinar morphogenesis and the inhibition of TGFBI-induced PC3 and C4-2B cell invasion by exogenous ECM-1 suggests that increased expression of ECM-1 in prostate cancer may be beneficial to patients, whereas the opposite may be true for TGFBI." (PMID 29858602, 2018). "In summary, in the contexts of prostate epithelial cell acinar morphogenesis and prostate cancer cell invasion, TGFBI and ECM-1 have tumor-promoting and tumor-suppressing functions, respectively." (PMID 29858602, 2018). "The correlation of ECM-1 and Dkk-3 expression in WPMY-1 cells, ECM-1 inhibition of TGFBI-dependent prostate cancer cell invasion and the correlation of ECM1 and DKK3 expression with relapse-free survival, suggest that ECM-1 also participates in the Dkk-3 defense mechanism." (PMID 29858602, 2018). "Additionally, the findings indicate that ECM1 and ENO1 may serve as potential targets for developing therapies for bone metastatic castration‐resistant prostate cancer." (PMID 39563492, 2025).
ulcerative colitis (6 papers, 2009 to 2022). An inflammatory bowel disease involving the mucosal surface of the large intestine and rectum. "Genotyping using a reliable number of ulcerative colitis cohorts (n = 905) determined a strong disease susceptibility locus at the ECM1 gene." (PMID 36553077, 2022). "In ulcerative colitis, an inflammatory bowel disease caused by mutations in Ecm1 is also treated with retinoids." (PMID 24391906, 2013). "Similarly, in UC (ulcerative colitis), genome-wide association studies (GWAS) have identified a total of 47 susceptibility loci, mutations in ECM1 (extracellular matrix protein 1) and amino acid variation on position 11 of HLA-DRβ1, which are specific to patients with UC." (PMID 25514560, 2014).